ENO2 (enolase 2)
Diseases named in the same sentence as ENO2 in open-access papers (continued):
Sharing a sentence is not in itself a finding about the gene and the disease.
tumor (890 papers, 1985 to 2026). "As an oncogene, Eno2 is associated with increased cell growth, metastasis, tumor progression, glucocorticoid resistance, the activation and enrichment of glycolysis, distant metastasis, and increased migration and invasion." (PMID 39861068, 2024). "Elevated Enolase 2 is linked to aggressive growth and metabolic reprogramming in colorectal and other cancers; its suppression may impair tumor energy production and foster treatment sensitivity." (PMID 41515404, 2025). "Finally, tumor mutational burden analysis was utilized to investigate the potential role of ENO2 in gene mutations in ccRCC." (PMID 37760940, 2023). "Immunohistochemical analysis of HCC tissue microarrays revealed significant overexpression of ENO2 in human HCC samples compared to adjacent para-tumor tissues." (PMID 40055330, 2025). "While less dramatic than the changes seen with CA125 or Mesothelin, reduced Enolase 2 expression reflects an impact on tumor metabolism, essential for cancer cell survival, proliferation, and adaptation to therapy." (PMID 41515404, 2025). "High expression of ENO2 in MSI-H CRC patients was associated with worse clinical outcomes, including increased tumor invasion depth (p = 0.007) and greater likelihood of perineural invasion (p = 0.015)." (PMID 38724951, 2024). "The results of IHC staining demonstrated ENO2 protein expression in tumor tissues is higher than that in adjacent normal tissues." (PMID 38724951, 2024). "Expression of wild‐type ENO2 was found to decrease tumor malignancy, in contrast to mutant K394 mimetic acetylation." (PMID 38967113, 2024). "Taken together, these data revealed that BRD9 activates transcriptions of ALDOC and ENO2 to enhance glycolytic metabolism and tumor progression in COAD." (PMID 35778964, 2023). "In Group 4, almost all the connections become activating except for Aldh3a2 and Eno2; which were found to be strongly downregulated in all the tumor subgroups confirming their role in cancer resistance." (PMID 37016281, 2023). "We measured the expression levels of miR-2110, ENO2, and IGF2BP3 in tissues, and compared to tumor adjacent tissues, the expression of miR-2110 was decreased; while, ENO2 and IGF2BP3 were upregulated in cancer tissues." (PMID 37644235, 2023). "Enolase 2 (ENO2), a recognized tumor biomarker for PCa, is responsible for converting 2-phosphoglycerate into phosphoenolpyruvate during the glycolytic process." (PMID 36339430, 2022). "Seven genes, PFKFB4, ALDOA, EGLN3, EHHADH, GAPDH, HMGCS2, and ENO2, related to tumor FDG uptake were revealed to have a good prognostic value for survival in HCC." (PMID 35174098, 2022). "Among the identified genes, ALDOB was associated with a low risk, while five genes (GPC1, ALDOC, ENO2, SERPINE1, and SLC2A3) were associated with a high risk of developing tumor malignancy." (PMID 33737938, 2021). "Further, secreted HDGF promotes tumor angiogenesis, while nuclear HDGF activates glycolysis-related proteins, including enolase 2 (ENO2) and solute carrier family 2 member 4 (GLUT4), followed by an increase in glycolysis to cause tumor growth in GC." (PMID 32429972, 2020). "In all genes except ENO2 (P = 8.473E−4), significantly higher 5hmC levels were observed in tumor samples." (PMID 30010036, 2018). "Consistent with limited effects of adipocyte ATGL inhibition on lipid uptake by the tumor cells, only modest reduction in mRNA levels of ENO2 and HK2 was revealed indicating limited impact on glycolytic phenotype in the tumor cells." (PMID 27588494, 2016). "Although to a lesser extent also HK2, ALDOA and ENO2 were identified as important players for tumor progression in vivo." (PMID 25932951, 2015). "Specific overexpression of enolase 2 (ENO2) promotes glycolytic metabolic reprogramming via activating the GSK3β/β-catenin/c-Myc signaling pathway, thus inducing macrophage polarization toward the M2 phenotype and creating a tumor-promoting microenvironment." (PMID 40703518, 2025).
tumor (continued). "In addition, the presence of circulating tumor cells (CTCs), circulating tumor DNA (ctDNA), and changes in the abundance of some proteins (CXCL10, ASPH, SPP2, ENO2, etc) all predicted the risk of postoperative recurrence 8-12." (PMID 39430252, 2024). "Furthermore, the identification of HIF-1α-mediated transcriptional regulation of ENO2 adds a crucial layer to our understanding of the metabolic adaptations crucial for tumor growth in the context of ccRCC." (PMID 37760940, 2023). "Although previous studies have reported that the behavior and prognosis of tumor patients may be influenced by immune infiltration, the interaction mechanism between ENO2, IGF2BP3, and the tumor microenvironment (TME) in CRC remains unclear." (PMID 37644235, 2023). "To explore whether the ENO2 gene contributes to the occurrence and development of cancer, we used bioinformatics techniques to analyze ENO2 expression in normal and tumor tissues using TCGA cohort with 33 cancer types." (PMID 36588153, 2023). "NEC-like IDH2 and NEC-like SMARCA4/ARID1A tumors also demonstrated strong overexpression of proteins specific for neurons or cells of the diffuse neuroendocrine system such as UCHL1, CRMP1 and ENO2, strongly indicating a neuroendocrine differentiation for both tumor classes." (PMID 36443295, 2022). "Although we clarified that circRHOBTB3 could inhibit CRC progression by repressing EMT and interacting with the metabolic enzymes ENO1 and ENO2, it is still a great challenge for us to target tumor-suppressive circRNAs for CRC therapy." (PMID 35148775, 2022). "Mechanistically, m6A modification enhanced the expression of hepatoma-derived growth factor (HDGF), which could activate solute carrier family 2 member 4 (GLUT4) and enolase 2 (ENO2) to potentiate aerobic glycolysis in tumor cells." (PMID 33879256, 2021). "Overexpressed HDGF protein can be secreted and promotes tumor angiogenesis, while nuclear HDGF stimulates the expression of glucose transporter type 4 (GLUT-4) and enolase 2 (ENO2) mRNAs, resulting in increased levels of glycolysis and subsequently causing tumor growth and liver metastasis." (PMID 32404927, 2020). "Knockdown of ENO2 suppressed tumor growth and liver metastasis in PDAC." (PMID 32398667, 2020). "As expected, NB5t primary cells showed increased expression of mesenchymal genes (NT5E, ENG, ACTA2, MME, CD44, VIM or ALPL), while NB5t tumor sample expressed mostly neuronal genes (TH, ENO2, NCAM1, DDC or CHGB) reflecting the neuroblastic phenotype of stage 4/M NB tumors." (PMID 29163787, 2017). "Finally, we wanted to verify whether knockdown of PFKFB3 or ENO2 would abrogate the tumor-promoting effects of PPFIA3." (PMID 34094943, 2021). "The results identified a correlation between three tumor antigens—CUL7, ENO2, and MPP2—and both prognosis and APC infiltration in patients with COAD." (PMID 40260289, 2025). "For instance, ENO2 has been shown to promote EMT through activating the Wnt/β-catenin pathway, thereby regulating tumour metastasis in SCLC." (PMID 39061144, 2024). "Functional and mechanistic investigations have corroborated that ENO2 is transcriptionally activated by HIF-1α, and it orchestrates tumor cell glycolysis to sustain the energy supply and promote the progression of ccRCC." (PMID 37760940, 2023). "In particular, we observed that 3D tumor spheroid growth implies the overexpression of ALDOC and ENO2 glycolytic enzymes concomitant with the enhanced consumption of glucose and fructose and the enhanced production of lactate." (PMID 36945054, 2023). "In our snATAC-seq data, we also observed motifs of HIF1A in the PFKP, ENO2, and HK1 open promoter regions that are more accessible in tumor cells, consistent with the previous reports of HIF1A regulating these genes." (PMID 36973268, 2023). "High BPTF can promote the chromatin accessibility within the promoter region of ENO2 and SRC, improving the glycolytic activity of tumor cells." (PMID 36967443, 2023).
tumor (continued). "Secreted HDGF promotes tumor angiogenesis, while nuclear HDGF activates glucose transporter type 4 (GLUT4) and enolase 2 (ENO2) expression, which is followed by increased glycolysis in GC cells." (PMID 38053093, 2023). "HDGF promotes tumor growth and liver metastasis by promoting tumor angiogenesis on the one hand and activating the expression of GLUT4 and ENO2 on the other hand, which results in promotion of glycolysis in GC cells." (PMID 35155557, 2022). "PKM, ENO2, and SLC16A3 have been researched to have important effects on promoting tumor progression." (PMID 36245978, 2022). "Secreted HDGF facilitated tumor angiogenesis, while nuclear HDGF stimulated ENO2 and GLUT4 expression, followed by increased GC cell glycolysis, promoting tumor growth and metastasis." (PMID 35711459, 2022). "Peri-necrotic and palisading tumor regions also exhibited elevated expression of hypoxia-response genes such as HILPDA, LDHA, ENO2, and DDIT3 relative to other regions." (PMID 35973991, 2022). "Clinical samples showed significant downregulation of the following genes: CPT2, ACAA2, HPGD and ALDH3A2, while the expression of ENO2, TDO2, CPOX, ACADL and PTPRG was significantly upregulated in the tumor tissue (p < 0.01)." (PMID 36230866, 2022). "It was found that eight proteins (ADD2, DEF6, DOK3, ENO2, FMNL1, MICALL2, PARVG, and PSTPIP1) in KIRC cancer were more highly expressed in tumor tissues (100%), compared with normal tissues." (PMID 36428765, 2022). "The activated networks (HIF1A, ESRRA, ESRRG) had many proteins that were increased in tumor tissues that overlapped between the three targets, such as ENO1/ENO2, ALDOA, and LDHA." (PMID 27128972, 2016). "In this study we examined the contribution of important HIF-responsive genes such as VEGF, CCND1, ANGPTL4, EGLN3, ENO2, GLUT1 and IGFBP3 to tumor growth in a xenograft model using immune-compromised nude mice." (PMID 24260413, 2013). "Moreover, it has been shown that a small proportion of CRPC tumour cells acquire a neuroendocrine phenotype with neuronal marker expression, including chromogranin A (CHGA), synaptophysin (SYP) or enolase-2 (ENO2)." (PMID 37875732, 2023). "The increased intracellular ratio L-lactic acid/Glucose monophosphate and D-Fructose monophosphate in all 3D tumor spheroids compared to their relative 2D cultures well agreed with the up-regulation of the glycolytic enzymes ALDOC and ENO2, at both gene and protein levels." (PMID 36945054, 2023). "Taken together, these data suggest that circRHOBTB3 might regulate intracellular ROS levels to inhibit tumor cell proliferation and EMT by interacting with metabolic enzymes such as ENO1 and ENO2." (PMID 35148775, 2022). "Notably, we found that cells in cluster four shows an increased expression of genes related to the hypoxia (e.g., HILPDA), tumor angiogenesis (e.g., VEGF and NRN1) and glycolytic (e.g., ENO2)." (PMID 34805184, 2021). "Knockdown of ENO2 significantly decreased tumor growth and tumor volume; however, the tumor growth inhibition was reversed by WT ENO2 but not by the K394-mutant." (PMID 32398667, 2020). "Either its function is not critical for tumor growth, or the remaining ENO1, or another activated compensatory pathway circumvents the loss of ENO2 protein." (PMID 24260413, 2013). "We further discovered that the lack of ANGPTL4, EGLN3 or ENO2 expression did not change tumor growth." (PMID 24260413, 2013). "Therefore, the elevated expression of ENO2 and IGF2BP3 in CRC may influence tumor immunity and contribute to carcinogenesis, providing implications for future research on immunotherapy." (PMID 37644235, 2023). "Western blotting data showed that the expression of ENO2, but not ENO1, was repressed by AP-III-a4 in tumor tissues, which was confirmed by IHC." (PMID 36588153, 2023).
cancer (189 papers, 1987 to 2025). A tumor composed of atypical neoplastic, often pleomorphic cells that invade other tissues. "Among the ENO isoforms, ENO1 and ENO2 have been identified in EVs associated with cancers of the breast and prostate." (PMID 40214422, 2025). "Among the three enolase isoforms, both enolase 1 (ENO1) and ENO2 encode crucial glycolytic metalloenzymes and are frequently associated with metastases and unfavourable prognoses in multiple cancer types." (PMID 39061144, 2024). "Among the PRCa genes expressed at the protein level are transcriptional regulators (Hdac2 and Hmga2), cancer-linked genes (Klf4 and Kit), and genes involved in glycolysis and pyruvate metabolism (Hk1, Eno2, and Pck2)." (PMID 22305566, 2012). "The suppression of the expression of GA-upregulated cancer proteins, including enolase-2, capping protein CapG, galectin-3, and cathepsin D, was observed after p70S6K1 downregulation/blockade." (PMID 40149589, 2025). "The first reported paralog SL interaction in cancer involves ENO1 and ENO2, encoding the glycolytic enzyme enolase." (PMID 38638566, 2024). "It has been reported that the downregulation of Myh3 and Eno2 in cancer patients is a good prognostic tool." (PMID 39861068, 2024). "They found that glycolysis-related genes, including lactate dehydrogenase A (LDHA) and enolase 2 (ENO2) expression profiles significantly changed between fibroblasts cocultured with highly metastatic cancer cells and low metastatic potential cancer cells." (PMID 38562556, 2024). "Enolase 2 (ENO2) is a crucial glycolytic enzyme in cancer metabolic process and acts as a “moonlighting” protein to play various functions in diverse cellular processes unrelated to glycolysis." (PMID 36588153, 2023). "Further analysis revealed that co-culturing with cancer cells induced a major shift in CAF metabolism with increased expression of genes involved in glycolysis (SLC2A, GAPDH, LDHA, SLC16A3, ENO2, CA12), and the Hallmark gene set glycolysis." (PMID 37261365, 2023). "Pan-cancer analysis showed significant differential expression of ENO2 in 12 TCGA tumors, including HNSCC." (PMID 36588153, 2023). "It has been reported that these genes were closely associated with cancer progression, including ENO1, PRKCB, ENO2, and PDK1." (PMID 35504868, 2022). "Enolase 2 (ENO2) is a key glycolytic enzyme in the metabolic process of glycolysis, which is associated with worsened prognosis in various cancer." (PMID 35780404, 2022). "It would be interesting to follow our patients with NEPC, who displayed elevated GABBR1 and ENO2 gene expression levels, to evaluate the cancer progression." (PMID 29980692, 2018). "Overexpression of ENO2 is sufficient to increase glycolysis in cancer cells." (PMID 39299930, 2024). "Notably, CD34, IL7R, NRP1, GZMB, FGF7, and ENO2 exhibited significant expression in cancer stem cells, CD4+ memory cells, regulatory T cells, NK cells, fibroblasts, and neurons, respectively." (PMID 38846945, 2024). "ENO2 is overexpressed and has been proposed to predict prognosis in a few malignant tumors 43-44." (PMID 38250157, 2024). "Intriguingly, the exact three glycolytic genes with the highest upregulation upon ESCRT-I deficiency (encoding HK2, ENO2 and PFKFB3) were reported to have increased expression in cancer-associated fibroblasts due to activation of JNK signaling upon compression-induced stress." (PMID 39560723, 2024). "ENO2 (enolase 2) is a critical glycolytic enzyme in cancer metabolic processes." (PMID 38605343, 2024). "Notably, however, MUC1-C-dependent, MYC-independent signaling was identified for induction of other genes, such as PFKL, ALDOA, and ENO2, that are essential for driving glycolysis and are upregulated in cancer." (PMID 37915591, 2023). "In summary, our findings suggest that ENO2 is a novel druggable target in HNSCC as blocking its function could strongly impair cancer cell proliferation due to reduced glycolysis and cell cycle arrest." (PMID 36588153, 2023).
cancer (continued). "The glycolytic enzyme enolase 2 (ENO2) is dysregulated in many types of cancer." (PMID 35954207, 2022). "Enolase 2 (ENO2) has increasingly been documented in multiple cancers in recent years." (PMID 36419844, 2022). "Overall, these results suggest that ENO2 is a potential prognosis biomarker of ccRCC and could affect the malignant biological behavior of cancer cells, highlighting its value as a potential therapeutic target." (PMID 36419844, 2022). "ENO2, also known as neuron-specific enolase, can be expressed by neuronal and cancer cells and may have an important role in glucose metabolism under hypoxic conditions." (PMID 34359798, 2021). "In addition, there were multiple genes induced that are involved with cell and organelle structure and function (PNCK, UBD, CDH2, HERC5) and importantly, genes associated with the prostate, AR (MMP7, CDH2, ENO2, IGFBP3) and cancer (IFIT3, IFI44L)." (PMID 29416764, 2018). "Transcriptome analysis showed that the expression of glycolysis-related genes, such as LDHA and ENO2, significantly changed in fibroblasts when they were cocultured with cancer cells with high metastatic potential compared to fibroblasts incubated with cancer cells with low metastatic potential." (PMID 32555715, 2020). "In the context of cancer biomarkers, proteins such as CA125/MUC16, Mesothelin and Enolase 2 are increasingly used not only for diagnosis and monitoring, but also as targets to evaluate therapeutic impact and prognosis in oncology." (PMID 41515404, 2025). "In ccRCC, the upregulation of ENO2 is regulated by FOXC1, which promotes glycolysis and supports the Warburg effect—a metabolic shift observed in many cancers where cells rely on glycolysis for energy production even in the presence of oxygen." (PMID 39348357, 2024). "The expression of ENO2 and IGF2BP3 in cancer tissues was higher than that in adjacent normal tissues." (PMID 37644235, 2023). "Three metabolic enzymes (EZH2, ENO2, and RRM2) were found to be commonly regulated by S-M, TF-M, and miR in all three cancers." (PMID 34790674, 2021). "By performing qRT-PCR, we observed that cancer cells exposed to SPP1 exhibited a significantly increased gene expression in EMT-related molecule CD44 and glycolytic genes including SLC2A1 and ENO2 at 48 h." (PMID 34676217, 2021). "The genes with CNV amplifications exhibited a significantly higher expression in cancer tissues than in normal controls (e.g., HK3 and ENO2), while the genes with CNV deletions exhibited significantly lower expression (e.g., ALDOB and PSAT1)." (PMID 33564363, 2021). "From this analysis, 10 commonly regulated genes were identified, and we validated the role of four genes (ENO2, EphB2, SerpinE1, and STX12), which were reportedly involved in cancer cell activities, as downstream targets of NFE2L1." (PMID 32942643, 2020). "Based on this study, we suggest that ENO2 acts as an oncogenic driver in HNSCC development and targeting it using the ENO inhibitor AP-III-a4 represents a potential therapeutic approach for treating this type of cancer." (PMID 36588153, 2023). "This highlights a metabolic vulnerability of GB cells lacking ENO1, in which ENO2 deletion has inhibited the growth, survival and tumorigenic properties of cancer cells." (PMID 37298093, 2023). "Moreover, knockdown of ENO2 remarkably inactivated AKT and ERK1/2 signaling, which was consistent with the results reported from other types of cancer." (PMID 36588153, 2023). "However, some signaling proteins were found to be common regulatory molecules among the three cancers whereas terminal enzymes, such as EZH2, ENO2, RRM2, and TYMS, were found to be commonly regulated in all the cancers by three different regulatory mechanisms." (PMID 34790674, 2021).